NOD1 (nucleotide binding oligomerization domain containing 1)
Diseases named in the same sentence as NOD1 in open-access papers (continued):
Sharing a sentence is not in itself a finding about the gene and the disease.
tumor (continued). "In the early stages, elevated expression of NOD1 and NOD2 can activate adaptive immune responses or induce apoptosis in tumor cells." (PMID 39329913, 2024). "When comparing the gene expression signature of poorly differentiated (G3) tumours with the moderately differentiated (G2) ones, the downregulation of RELA, NOD1, CASP8, BCL2L1, ELK1, and IKBKB was found." (PMID 36433652, 2022). "HNSCC tumor progression is promoted by IL-8 via various mechanisms, such as the activation of MAPK/NF-κB and NOD1/RIP2 pathways and the reduction of JNK." (PMID 36143043, 2022). "In this study, we revealed that a relatively new PRR, NOD1, was activated by CRC‐EVs, consequently inducing inflammatory responses in macrophages to promote tumour cell migration." (PMID 36068649, 2022). "A decrease in the levels of RELA, NOD1, CASP8, BCL2L1, ELK1, and IKBKB was identified in the poorly differentiated (G3) tumours compared with the moderately differentiated (G2) ones." (PMID 36433652, 2022). "In addition, our data suggests that NOD1 may act as a tumor suppressor gene (HR< 1) in LUAD." (PMID 36277882, 2022). "Given that tumour cell‐derived EV‐activated PRRs induce inflammatory responses to promote metastasis and NOD1 activation has been implicated in CRC metastasis, we next explored whether CRC‐EV‐mediated NOD1 activation could promote CRC cell growth and migration." (PMID 36068649, 2022). "In this model, NOD1 overexpression reduced estrogen-induced tumor proliferation, while NOD2 activation led to a remarkable suppression of tumor growth." (PMID 34899721, 2021). "We confirmed that Evo had an anti-tumor effect in HepG2 and SMMC-7721 cells, possibly via suppressing the NOD1 pathway, both in vitro and in vivo." (PMID 30384473, 2018). "Conversely, heightened expression of NOD1 and NOD2 may exacerbate systemic inflammation by triggering an excessive release of inflammatory factors, thereby promoting tumor growth, metastasis, and invasion." (PMID 39329913, 2024). "Both NOD1 and NOD2 exhibit dual effects on tumor cells, which may vary depending on the tumor type and stage." (PMID 39329913, 2024). "A significant upregulation of NOD1 expression was observed in primary tumour tissues and metastatic liver tissues compared to that in normal tissues." (PMID 36068649, 2022). "Next, we quantified NOD1 expression in tumour tissues from CRC patients without liver metastasis (CRC‐NLM) and found that the level of NOD1 was also increased in tumour tissues." (PMID 36068649, 2022). "Moreover, a decrease in the levels of RELA, NOD1, CASP8, BCL2L1, ELK1, and IKBKB was identified in poorly differentiated tumours compared to moderately differentiated tumours." (PMID 36433652, 2022). "CASP8, CASP6, GSDME, NOD1, and GPX4 were significantly upregulated in tumor tissues compared to the normal tissues, whereas IL6, IL1B, NLRP3, and NLRC4 were downregulated, suggesting that pyroptosis-related genes play important roles in tumor progression and prognosis." (PMID 35559014, 2022). "A total of 24 pyroptosis-related genes shown significantly different expression between normal and tumor tissues in COAD and seven genes (CASP4, CASP5, CASP9, IL6, NOD1, PJVK, and PRKACA) screened by univariate and LASSO cox regression analysis were used to construct the risk model." (PMID 34938319, 2021). "The nucleotide-binding oligomerization domain protein-1 (NOD1), one of the most important members of the NOD-like receptor (NLR) family, can induce pro-inflammatory responses and is involved in the apoptotic signaling pathway in some tumor cells." (PMID 34627252, 2021). "NOD1, a relatively new PRR that recognizes iE-DAP derived from gram-negative and gram-positive bacterial wall, plays an important role in host defense and inflammation and has recently been shown to promote tumor development." (PMID 31956962, 2020). "In addition, the tumor also had genomic alterations in NOTCH1 L2457V (designated as a benign genomic alteration in ClinVar) and NOD1 L475fs*35." (PMID 31362756, 2019).
tumor (continued). "Researchers have gathered data of NOD1 levels in the GEO database and revealed that NOD1 expression differed significantly between tumor and non-tumor tissue." (PMID 30384473, 2018). "From gathering data of NOD1 levels in the GEO database, researchers revealed that NOD1 expression differed significantly between tumor and non-tumor tissue." (PMID 30384473, 2018). "Elucidation of NOD1 and NOD2 effects on tumor cell viability and proliferation may unveil potential targets for future therapeutic intervention." (PMID 29615116, 2018). "Besides, we observed that activation of the NOD1/NF-κB signaling pathway by L. intestinalis did not have an accelerating effect on tumor cell proliferation." (PMID 39773173, 2025). "To determine whether NOD1 and/or NOD2 play a similar tumor suppressor role in an ER-negative breast cancer cell, we decided to overexpress these receptors in the highly invasive TNBC-derived Hs578T cell line in order to evaluate their impact in breast tumorigenesis in vitro." (PMID 30791886, 2019). "Therefore, we investigated whether NOD1 and/or NOD2 might act as a tumor suppressor in this cell model." (PMID 29615116, 2018). "Furthermore, we followed by RT-PCR the expression of four selected genes, namely Pten, Hmox1, E2f7 and Nod1 in LLC as well as in other cancer cell lines of human origin, in order to reveal potential common patterns of response to mastic oil among different tumor types." (PMID 20003503, 2009). "CCL14, FYN, NOD1, and GDF10 mRNA expressions were decreased in tumor tissues compared with the adjacent non-tumor tissues." (PMID 38602568, 2024). "Scatter plots of NOD1, NOD2, and NLRX1 mRNA expression level in the GEO database revealed that only NOD1 expression differed significantly between tumor and nontumor tissue (P = 0.007)." (PMID 28960882, 2017).
cancer (61 papers, 2009 to 2026). A tumor composed of atypical neoplastic, often pleomorphic cells that invade other tissues. "NOD1 has been implicated in various inflammatory disorders and is gaining attention for its role in cancer." (PMID 41363048, 2025). "Several independent lines of evidence show that NOD1 expression is associated with cancer progression and malignant transformation." (PMID 38437016, 2024). "As expected, overexpression of NOD1 disrupted signaling pathways related to immune response and inflammation, some of which have been implicated in a variety of cancers." (PMID 30791886, 2019). "The dysregulation of NOD1 signaling can cause persistent infection and chronic inflammation due to insufficient pathogen clearance, while chronic inflammation can initiate and promote cancer development." (PMID 37151389, 2023). "NOD1 is also involved in the apoptotic signaling pathway and mutates in many cancer cells." (PMID 32021648, 2020). "Not only is NOD1 important in host defense and autoimmune diseases, but recently, it has also been implicated in tumorigenesis for a number of cancers, including gastric cancer, head and neck carcinomas, oral squamous cell cancer, prostate adenocarcinoma, and lung cancer." (PMID 31956962, 2020). "As Salmonella ΔmsbB is under investigation as an anti-cancer vaccine strain, our results indicate that this strain may cause inflammatory complications at least in persons with mutations in Nod1 or Nod2 pathways." (PMID 25423082, 2014). "Recurrent insertions were located near cancer-associated genes, including RB1, NEDD4, FTO, LAMA2, NOD1, and KCNB2, implicating LINE-1 activity in cis-regulatory remodeling of oncogenic pathways." (PMID 41681929, 2026). "Previous studies have demonstrated that NOD1 is abnormally expressed in various tumors and can play a role in cancer diagnosis, monitoring, resistance, and prognosis." (PMID 41363048, 2025). "NOD1 activation increases cancer cell migration, metastasis, and adhesion in colon and liver cancers." (PMID 38437016, 2024). "Eight genes were consistently upregulated by >1.5-fold, of which NOD1 was the most significantly upregulated gene in tumors of NR, suggesting that a potential role of NOD1 in ETBF-increased cancer cell stemness." (PMID 38437016, 2024). "Biopsy results of nasal cancer and HNC have shown that cancer cells first show consistent and strong expression of NOD1 and NAIP, while normal epithelial cells show a broader NLR spectrum with the presence of NOD1, NOD2, NLRP1, NLRP3, and NAIP." (PMID 39403369, 2024). "The results showed that NOD1-knockdown significantly inhibited ETBF or BFT-1-induced BCSC enrichment and suppressed the ETBF or BFT-1-induced upregulation of stemness genes, suggesting that NOD1 mediated ETBF or BFT-1-enhanced cancer cell stemness." (PMID 38437016, 2024). "Evaluation of the ability of BFT-1 to bind to NOD1 using binding assays showed that the specific binding of HIS-BFT-1 was markedly higher in NOD1-overexpressing cancer cells than in empty vector (EM)-expressing cancer cells." (PMID 38437016, 2024). "In NOD1-overexpressing (NOD1) cancer cells treated with HIS-BFT-1 or HIS peptide, BFT-1 was localized at the plasma membrane as detected by immunofluorescence." (PMID 38437016, 2024). "F. nucleatum can also invade ESCC cancer cells and promote cancer progression through the NOD1/RIPK2/NFκB pathway." (PMID 36033476, 2022). "Clear cell renal cell carcinoma is another example of the involvement of NOD1 in cancer processes, although it is related to the pathogenesis of another organ—the kidney." (PMID 34066406, 2021). "Patients with these cancers would benefit from immunomodulatory nutrition strategies targeting NOD1." (PMID 34066406, 2021). "The NOD1–cancer axis has been widely confirmed and it is quite relevant due to the high morbidity and mortality associated with these diseases." (PMID 34066406, 2021).
cancer (continued). "This pattern was also observed with murine MC38 cancer cells, suggesting a generalized mechanism in adhesion upon NOD1 activation." (PMID 31956962, 2020). "This is the first study implicating NOD1 in cancer metastasis, and thus identifying this receptor as a putative therapeutic target." (PMID 31956962, 2020). "Based on these data, we conclude that downstream signaling and adhesive properties of NOD1 activation is p38 dependent in HT29 cancer cells." (PMID 31956962, 2020). "Although the pattern of NOD1 signaling in normal cells is well established, very little is known of its downstream signaling in cancer cells." (PMID 31956962, 2020). "Clinically, we confirm the link between high NOD1 expression and poor overall cancer survival using TCGA mRNA and human tissue microarray (TMA) of CRC." (PMID 31956962, 2020). "Both NOD1 and NOD2, altering the balance of anti- and pro-inflammatory cytokines, can modulate the risk of cancer development." (PMID 33324568, 2020). "Incidentally, the NOD1 antagonist salutaxel currently holds the status of an investigational new drug for cancer therapy." (PMID 30548868, 2019). "The purpose of this review is, therefore, to evaluate NOD receptors as new targets in cancer immunotherapy and to highlight the NOD1 and NOD2 agonists as well as antagonists reported to exhibit anticancer activity." (PMID 30548868, 2019). "A number of NOD1 and NOD2 SNPs have been associated with a higher risk of cancer development in many malignancies." (PMID 30837326, 2019). "Our data show that specific TKIs used in cancer also inhibit Nod1-Ripk2 immunometabolism responses indicative of metabolic disease." (PMID 28484277, 2017). "By altering the balance between pro- and anti-inflammatory cytokines, NOD1 and NOD2 modulate the risk of cancer." (PMID 28771183, 2017). "Polymorphisms of the NLR genes NOD1 (NLRC1) and NOD2 (NLRC2) have been correlated with altered cancer risk." (PMID 24681825, 2014). "Based on our above findings that NOD1 was a functional receptor of BFT-1 and was stabilized by BFT-1, we speculated that high NOD1 expression might increase cancer cell stemness and chemoresistance." (PMID 38437016, 2024). "In addition, RNF34 possesses the ability to hinder cancer cell apoptosis through the regulation of the NOD1 pathway." (PMID 38410284, 2024). "The involvement of NOD1 in cancer progression remains controversial." (PMID 38437016, 2024). "These studied coupled with our RNAseq data indicated NOD1 might serve as a valuable indicator related to cancer progression and malignant transformation." (PMID 38437016, 2024). "Our HOXC10 /NOD1/ERK axis pathway fits with NOD1 regulating of cancer metastasis." (PMID 39191757, 2024). "Although the roles of TLRs in the progression of liver injury and cancer are being actively investigated, it remains largely unknown whether activation of NOD1 and NOD2 is beneficial or harmful in these diseases." (PMID 36268029, 2022). "However, in our research, NOD1 showed a significant cancer suppressive effect and acted as a protective factor against AML." (PMID 36034801, 2022). "We have demonstrated NOD1 as novel targets in inflammation-mediated cancer metastasis." (PMID 31956962, 2020). "Hence, NOD1 activation enables cancer cells to fulfill two key steps in metastasis: adhesion and migration." (PMID 31956962, 2020). "Hence, we surmised that p38 MAPK was more important for NOD1 downstream signaling in CRC cancer cells." (PMID 31956962, 2020). "The NOD1 pathway is expressed in most tissues, including cancer cells." (PMID 30384473, 2018). "Upon DAP recognition by NOD1, an immune inflammatory response is generated via NF-κB and mitogen-associated protein kinases (MAPKs), while DAP has also been implicated in other innate immunity mechanisms, such as apoptosis and autophagy, as well as cancer metastasis." (PMID 35811665, 2022).
cancer (continued). "In recent years, emerging evidence has highlighted the crucial roles played by NOD1 and NOD2 in regulating infectious diseases, metabolic disorders, cancer, and autoimmune conditions, among others." (PMID 39329913, 2024). "NOD1 and NOD2 are widely expressed in immune cells and serve as crucial PRRs, demonstrating dual roles in cancer regulation." (PMID 39329913, 2024). "NOD1 and NOD2 represent promising targets for cancer therapy, warranting a comprehensive understanding of their alterations across distinct stages and phenotypes, which holds paramount significance." (PMID 39329913, 2024). "In the cervical tissues of patients with metastatic cervical squamous cell carcinoma (CSCC), NOD1 and NOD2 exhibit pronounced upregulation, thereby facilitating cancer cell proliferation and metastasis." (PMID 39329913, 2024). "NOD1, a member of the pattern recognition receptor (PRR) family, is involved in various pathologies, especially cancer." (PMID 36920176, 2023). "Unlike NOD1/2 inhibitors, targeting the downstream protein of NOD1/2 signaling pathway, RIPK2, to fight against cancer is more advantageous for the following three reasons." (PMID 37324457, 2023). "The online GEPIA tool analysis TCGA database indicates that the expressions of Groα, NOD1, NOD2 and RIPK2 in the cancer sample (n=519) are higher than those of in the normal tissue (n=44)." (PMID 37151389, 2023). "Further elucidation of the molecular mechanisms by which NOD1 and NOD2 activation regulate the development of liver injury and cancer is required for the application of NOD1 and NOD2 ligands as treatments of human diseases." (PMID 36268029, 2022). "GO and KEGG enrichment analyses further showed that the genes and proteins correlated with the upregulation of NOD1 or NOD2 were involved in cell proliferation, cytokines, and pathways in cancer such as ERK, NF-κB, and IL-8." (PMID 35130902, 2022). "However, despite the direct relationship of NOD1 with different immunometabolic chronic diseases and cancer, it is still almost completely unknown today in relation to its potential modulation through immunonutritional strategies as aids to biomedical interventions." (PMID 34066406, 2021). "In our study, drug-sensitivity analysis revealed that the expression of NLRP7, NLRP2, NOD1, and CASP6 was positively correlated with some or most drugs in the cancer therapeutic response portal database." (PMID 34226539, 2021). "However the role of NOD1 in cancer metastasis is entirely unknown." (PMID 31956962, 2020). "While emerging data suggest nucleotide oligomerization domain receptor 1 (NOD1), a cytoplasmic pattern recognition receptor, may play an important and complementary role in the immune response to bacterial infection, its role in cancer metastasis is entirely unknown." (PMID 31956962, 2020). "As CRC often metastasize to the liver via the portal circulation, intrasplenic injection of cancer cells closely mimics this process and allows for the examination of the CRC metastasis under NOD1 activation and inhibition." (PMID 31956962, 2020). "To conclude, the innate immune receptors NOD1 and NOD2 constitute promising targets in cancer immunotherapy." (PMID 30548868, 2019). "Based on the central role of NOD1 and NOD2 in these cellular surveillance pathways, these receptors have been proposed as tentative targets for immunomodulation of cancer." (PMID 30791886, 2019). "Both NOD1 and NOD2 are thought to engage not only in innate and adaptive immune responses, but also in the interaction between autophagy and cancer." (PMID 28771183, 2017). "While NOD1/2 typically participates in immune responses, oxidative stress from Ar-CAP could also trigger this pathway in cancer cells, helping to manage oxidative damage and maintain survival under stress." (PMID 39857768, 2025).